BRAF (B-Raf proto-oncogene, serine/threonine kinase)
Diseases named in the same sentence as BRAF in open-access papers (continued):
Sharing a sentence is not in itself a finding about the gene and the disease.
cutaneous melanoma (continued). "Those therapies are used according to the molecular profile of the tumors, and cutaneous melanomas with BRAF V600 mutations are likely to benefit from the combination of BRAF (vemurafenib, dabrafenib) and MEK inhibitors (trametinib)." (PMID 31262050, 2019). "MiR-146a acts in the first phases of cancerogenesis in BRAF/NRAS-mutated cutaneous melanoma through NOTCH proteins." (PMID 31683701, 2019). "Systemic treatment options are limited, as targetable BRAF mutations are rare compared to cutaneous melanoma." (PMID 31500314, 2019). "In CjM, NRAS mutations are mutually exclusive with BRAF mutations, similarly to cutaneous melanoma, in which concomitant BRAF and NRAS mutations occur in less than 0.6% of cases." (PMID 31683701, 2019). "These BRAF mutations found in CjM are similar to cutaneous melanoma, in which V600E represents the most typical mutation (almost 70% of cases), followed by V600K (about 20% of cases) and less frequent mutations, such as V600D and V600R." (PMID 31683701, 2019). "Identification of the V600E canonical BRAF mutations in human cutaneous melanoma led to the development of efficacious small molecule inhibitors." (PMID 29385676, 2018). "BRAF inhibitors target the BRAF-V600E/K mutated kinase, the driver mutation found in 50% of cutaneous melanoma." (PMID 30429474, 2018). "The patient with MUP harbored a v-Raf murine sarcoma viral oncogene homolog (BRAF) V600E mutation and was assigned to the group of cutaneous melanomas." (PMID 29988983, 2018). "We observed a significant association in our study between BRAF p.V600M (c.1798G>A) and signature 7 in skin cutaneous melanoma." (PMID 30412573, 2018). "This is similar to the situation in cutaneous melanoma where the co-occurrence of NF1 with BRAF, RAS and other mutations is well recognised." (PMID 29559732, 2018). "The majority of human cutaneous melanomas are driven in part by constitutive activation of the MAPK pathway through mutation of genes such as BRAF, NRAS, NF1, KIT, GNAQ, and GNA11, often in a mutually exclusive pattern." (PMID 30188888, 2018). "The occurrence of TERTp mutations in cutaneous melanoma associates with BRAF mutations and with poorer prognostic features, such as higher Breslow’s thickness, higher mitotic rate, presence of ulceration, absence of regression, and lymph node metastases." (PMID 29751586, 2018). "While more than 80% of human cutaneous melanomas are BRAF-mutated, this alteration is less frequent and poorly documented in dogs." (PMID 30514258, 2018). "Approximately 90% of human cutaneous melanomas are driven in part by BRAF, RAS, NF1, and KIT mutations that confer constitutive mitogenic signaling through the MAPK pathway." (PMID 30188888, 2018). "Approximately 50% of cutaneous melanomas have BRAF (V600E) mutation, and most of them respond well to BRAF inhibitor (BRAFi) treatment (vemurafenib or dabrafenib)." (PMID 29094484, 2017). "According to previous studies, cutaneous melanomas with mutations in RAS had less lymphocytic infiltration than those with the BRAF mutation." (PMID 28107203, 2017). "Approximately 40-50% of the cutaneous melanomas harbor oncogenic driver mutations at V600 codon in the serine-threonine kinase BRAF and this mutation induce constitutive activation of the MAPK signaling pathway." (PMID 28416755, 2017). "A BRAF‐V600E antibody has recently been commercialized, and it is sensitive and specific in detecting BRAF‐V600E mutation in cutaneous melanomas." (PMID 28293477, 2017).
cutaneous melanoma (continued). "Somatic mutations of BRAF or NRAS activating the MAP kinase cell signaling pathway are present in 70% of cutaneous melanomas." (PMID 28668077, 2017). "Somatic mutations in the RAS/RAF/MEK/ERK signaling pathway are frequent in cutaneous melanomas, with 50%–70% of them being BRAF mutations." (PMID 28124977, 2017). "From 43 to 66% of cutaneous melanomas carry BRAF mutations, among which the BRAF V600E transversion is the most common (80%), followed by V600K (12%), V600R (5%), V600M (4%), and V600D (<5%)." (PMID 28484715, 2017). "Why KRAS mutations prevail in colorectal, lung and pancreatic cancer, while NRAS or BRAF are mutated more frequently in skin melanoma, and HRAS mutations are predominant in head and neck squamous cell carcinoma is not yet clear." (PMID 28152508, 2017). "Somatic BRAF mutation in codon 600 of exon 15 occurs in 40–50% of cutaneous melanomas, with V600E the most common mutation." (PMID 29120401, 2017). "Mucosal melanoma differs from cutaneous melanoma not only in terms of poorer clinical outcome but also on the molecular level having e.g. less BRAF and more frequent KIT mutations than cutaneous melanomas." (PMID 28380455, 2017). "In the common clinical practice, all patients with advanced cutaneous malignant melanoma who meet the criteria for treatment with a BRAF inhibitor are tested for the presence of the BRAF mutation." (PMID 27520988, 2016). "Instead of common occurence of BRAF or NRAS mutations in cutaneous melanoma, few cases of UM harbor BRAF and NRAS mutations." (PMID 26940009, 2016). "BRAF mutation at V600E is present in 40-60% of cutaneous melanomas and can be treated with BRAF inhibitor (BRAFi) (vemurafenib or dabrafenib) or combined BRAFi and MEK inhibitor (MEKi)." (PMID 26771234, 2016). "Overall, variants in the final reference standard parallel the BRAF subtype of cutaneous melanomas, the largest genomic sub-group reported by TCGA21, and which is defined by point mutations at BRAF V600 and K601." (PMID 27094764, 2016). "Half of cutaneous melanomas harbor activating mutations in BRAF and the most abundant is BRAFV600E followed by BRAFV600K." (PMID 27520988, 2016). "In contrast, half of cutaneous melanomas have BRAF mutations and treatment with BRAF inhibitors is established for patients with disseminated disease." (PMID 27520988, 2016). "BRAF mutations were seen in 57% of human cutaneous melanomas and NRAS was mutated in 17% of samples." (PMID 29056717, 2016). "Approximately 40% of cutaneous melanoma patients have tumors with an activating mutation in the BRAF gene (BRAF V600E/K), which activates the MAPK pathway via a phosphorylation cascade that activates MEK and ERK." (PMID 26426052, 2015). "Since the discovery of gain of function mutations in the proto-oncogenes NRAS and BRAF, thousands of human skin melanoma samples have been analyzed, and the estimated incidence of NRAS and BRAF mutations are 18 % and 41 %, respectively." (PMID 26141748, 2015). "This disease differs from the cutaneous counterparts for its biology and genetic features as is the case of BRAF, which is often mutated in cutaneous melanoma and rarely in MM." (PMID 26161400, 2015). "The vast majority of cutaneous melanomas show activating mutations in BRAF proto-oncogenes, sustaining proliferative stimuli." (PMID 25474135, 2015). "Approximately 40 to 60 % of cutaneous melanomas carry mutations in the BRAF gene (V600E), which leads to the constitutive activation of downstream signaling through the MAPK pathway." (PMID 26376781, 2015). "Looking beyond combinations involving mutant EGFR or KRAS, we found that BRAF mutations in skin cutaneous melanoma (SKCM) were negatively associated with NRAS." (PMID 26047463, 2015). "We sought to evaluate the importance of these genes in a comparable tumor, such as cutaneous melanoma with BRAF-mutation." (PMID 26397223, 2015).
cutaneous melanoma (continued). "Because cutaneous melanomas often carry activating mutations in the BRAF gene (V600E), we performed a BRAF mutational analysis using direct sequencing for both of these tumors arising from the lung." (PMID 26376781, 2015). "The reported frequency of BRAF mutations varies between 40 and 70% in cutaneous melanoma and these are most frequently detected in tumors occurring in skin that is not chronically damaged by the sun." (PMID 24959217, 2014). "A novel therapeutic approach has been suggested for advanced-stage cutaneous melanoma, whereby a BRAF mutation at codon 600 has been identified, leading to a novel approach for drug development in the advanced setting." (PMID 25120707, 2014). "By contrast, as previously demonstrated, gene mutations for cutaneous melanomas were irrelevant in vulvar melanomas (BRAF, NRAS), indicating that these two diseases have a different origin." (PMID 24535703, 2014). "Previous studies have revealed that cutaneous melanomas showed oncogenic mutations in some components of the MAPKinase cascade, particularly in BRAF and NRAS." (PMID 25280020, 2014). "It is now well established that the frequency of detected BRAF V600E mutations in cutaneous melanoma is influenced by the analytical sensitivity of the method applied for their detection." (PMID 25037456, 2014). "V600E, a protein substitution of valine for glutamic acid at position 600 (Val600Glu), is the most common BRAF mutation observed in cutaneous melanoma, which consists of a T1799A transversion mutation in exon 15 of this gene." (PMID 25120707, 2014). "Frequently, NRAS and BRAF mutations have been observed in cutaneous melanoma and in subsets of mucosal melanoma." (PMID 25120707, 2014). "Gene mutations in cutaneous melanoma (BRAF, N-Ras, etc.)were entirely different from those in uveal melanoma (GNAQ, GNA11, etc.)." (PMID 25184134, 2014). "As a comparison, over 40% of cutaneous melanoma samples carry a mutation in BRAF, 90% of which are at the hotspot V600E." (PMID 25484917, 2014). "An exploratory analysis within the patients with cutaneous melanoma, positive for BRAF V600E mutation, (N = 7) identified a stronger trend between lower CMCs (≤ 100/mL of blood) and increased survival (p = 0.06)." (PMID 24811334, 2014). "Mutations in the BRAF kinase are the most commonly identified, seen in between 40 and 50% of cutaneous melanomas, in particular at the V600 position." (PMID 24693430, 2014). "Somatic mutations in BRAF gene have been described as key genetic alterations in skin melanoma development, whereas GNAQ gene was described as an oncogene in uveal melanomas." (PMID 23904987, 2013). "In a previous report we described MAPK and AKT/mTOR pathway activations in a series of skin melanomas, where an association between BRAF mutation and high mTOR pathway activation was observed." (PMID 23904987, 2013). "BRAF mutations at the V600 residue are the predominant MAPK activating mutations found in cutaneous melanoma." (PMID 22699362, 2013). "Somatic mutations in GNAQ gene were described as being the main oncogenic activation in uveal melanomas, whereas mutations in BRAF gene have been described as a key genetic alteration that contributes to skin melanoma development." (PMID 23904987, 2013). "Somatic mutations in the BRAF oncogene have been documented with high frequency in cutaneous melanomas, occurring in 50 to 70% of tumor samples." (PMID 23555633, 2013). "In a previous work we reported BRAF mutations in 30% of skin melanomas and GNAQ gene mutations in 36% of uveal melanomas." (PMID 23904987, 2013). "In contrast to cutaneous melanomas, the relevance of BRAF (T1799A→V600E) mutations for MAPK activation in uveal melanoma is less clear." (PMID 22808163, 2012).
cutaneous melanoma (continued). "V-RAF murine sarcoma viral oncogene homolog B1 (BRAF) is a serine/threonine-specific protein kinase that is mutated with high frequency in cutaneous melanoma, and many other cancers." (PMID 20667740, 2010). "Among primary cutaneous melanomas, the highest prevalence of BRAF oncogenic mutations has been reported in late stage tumors (mostly, vertical growth phase lesions)." (PMID 19828018, 2009). "On the one hand, comparable incidence of activating BRAF mutations in invasive cutaneous melanomas and benign melanocytic nevi indicate that BRAF mutations alone are insufficient to cause malignant transformation." (PMID 18631381, 2008). "Although the results of this study confirm that the BRAF mutation is heterogeneously distributed in uveal melanoma the frequency of this mutation still appears considerably lower than in cutaneous melanoma." (PMID 18985043, 2008). "Mutations in the BRAF gene (a member of the Raf family that encodes a serine/threonine protein kinase) have been shown to occur in the majority of cutaneous melanomas." (PMID 18985043, 2008). "Activating mutations in the BRAF gene have been identified in many human cancers, with the highest frequency of mutations found in cutaneous melanomas." (PMID 18985043, 2008). "Recent reports refer that there is a high incidence of activating mutations in the kinase domain of the BRAF gene in malignant melanoma of the skin while in CCSTA the BRAF mutations are rare." (PMID 16893467, 2006). "It has emerged that BRAF (v-raf murine sarcoma viral oncogene homologue B1) is very frequently activated by mutation in cutaneous melanomas." (PMID 15928660, 2005). "Non-V600 mutations occur in 11 % and BRAF fusions in 3 %–6 % of cutaneous melanomas." (PMID 41450449, 2026). "BRAF mutations are found in a small percentage of AMM in comparison to cutaneous melanomas." (PMID 40320509, 2025). "Among 41 patients with unresectable advanced/metastatic BRAF mutation-positive cutaneous melanoma treated at one of 5 hospitals in 2016-2018, ICIs were the most common 1L treatment (70.7% of regimens) and the most common treatment overall (52.9% across multiple lines of therapy)." (PMID 40677709, 2025). "Interestingly, only 128 (28%) of the 449 WES samples in our meta-cohort had a BRAF:V600 alteration, while the expected prevalence of such a mutation is approximately 50% in cutaneous melanoma." (PMID 40075562, 2025). "Molecular profiling may further support treatment tailoring by identifying actionable mutations (e.g., c-KIT, NRAS, or BRAF), although their prevalence is lower than in skin melanomas." (PMID 40875164, 2025). "BRAF mutation analysis was performed in 84 patients with stage III or IV cutaneous melanoma." (PMID 40994966, 2025). "The BRAF [L577I] mutation has been reported in cutaneous melanoma and is characterized as variant with ‘Unknown Oncogenic Effect’ in OncoKB." (PMID 39876058, 2025). "Although the overall mutation frequency of KRAS in cutaneous melanoma may be less pronounced than that of BRAF or NRAS, the current findings reinforce the concept that KRAS pathway activation is sufficiently relevant to warrant deeper examination." (PMID 40607411, 2025). "UM often has changes in the GNAQ and GNA11 genes, which may turn on mitogen‐activated protein kinase (MAPK) like BRAF mutations do in cutaneous melanoma." (PMID 41392397, 2025). "Analysis of cutaneous melanoma data in The Cancer Genome Atlas has shown that the prevalence of BRAF mutations is ~45% (90% of which is V600E), followed by a prevalence of the NRAS oncogene exon 3/codon 61 of 15–20%, while other RAS mutations are less frequent (KRAS, HRAS)." (PMID 40361349, 2025). "Acral and mucosal melanomas are also less likely to harbor BRAF mutations than cutaneous melanoma." (PMID 38529706, 2024). "However, the incidence of BRAF mutation is approximately 20% and 6% in acral and mucosal melanoma, respectively, being much lower than that registered in cutaneous melanoma." (PMID 38541077, 2024).
cutaneous melanoma (continued). "NRAS and BRAF mutations are frequently observed in cutaneous melanoma." (PMID 37861097, 2024). "Here, we conducted a sensitive ddPCR analysis to detect and quantify ctDNA in plasma samples prospectively and serially collected from resected BRAF-mutated cutaneous melanoma (CM) patients during targeted therapy with BRAF and MEK inhibitors, or immunotherapy, in adjuvant setting." (PMID 39609824, 2024). "Among cutaneous melanoma cases, 76% had BRAF mutations, and 8% had NRAS mutations." (PMID 39564955, 2024). "Surgery and possible adjuvant therapy, with either systemic immunotherapy or targeted therapy, are still considered the treatment of choice in cutaneous melanoma, with good prognosis depending on the stage of the disease, BRAF mutation status, and risk of recurrence." (PMID 38778387, 2024). "Thus, our study highlights a dual role of BRAF V600 mutations in cutaneous melanoma: one related to sustaining tumor growth and another linked to the modulation of the immune response." (PMID 38396984, 2024). "Consequently, our study emphasizes a dual role of BRAF mutations in cutaneous melanoma—one linked with the promotion of tumor growth and another associated with modulation of the immune response." (PMID 38396984, 2024). "As mentioned, the most frequently mutated genes in cutaneous melanoma are BRAF and NRAS." (PMID 38396984, 2024). "In contrast to cutaneous melanoma, BRAF mutations are infrequent in mucosal melanoma." (PMID 39001457, 2024). "BRAF is a proto-oncogene belonging to the RAF family of serine-threonine protein kinases; 50% of patients with cutaneous melanoma have BRAF mutations, with the glutamic acid for valine substitution at position 600 (V600E) representing about 90% of all BRAF mutations." (PMID 38450188, 2024). "To test this hypothesis, we treated A2058 and SK-MEL-28 human cutaneous melanoma cells, which harbor the BRAF (V600E) mutation, with RC48 alone or in combination with dabrafenib." (PMID 38594618, 2024). "In order to correlate our assessment of risk score with other established prognostic markers, several well established prognostic markers such as transcriptomic classification, mutation subtype and BRAF mutant for cutaneous melanoma were obtained from the previous TCGA study." (PMID 38475660, 2024). "Activating BRAF mutations are present in approximately 50% of cutaneous melanomas, and eligible patients receiving a combined BRAF/MEK-inhibitor therapy have a response rate of approximately 70%9,10 though these responses are not as durable as the ones observed by immunotherapy." (PMID 39661469, 2024). "Additionally, non-cutaneous melanomas are characterized by lower rates of targetable mutations in BRAF and NRAS." (PMID 39416390, 2024). "Approximately 50–60% of cutaneous melanomas harbor BRAF mutations, predominantly V600E." (PMID 38650694, 2024). "Hyperactivation of the MAPK (mitogen-activated protein kinase) RAF/MEK/ERK signaling pathway is commonly observed in cutaneous melanomas due to NRAS or BRAF mutations, and systemic treatment in these cases may include BRAF and MEK inhibitors." (PMID 37259298, 2023). "However, in a previous study, although 50–60% of patients with cutaneous melanoma have a BRAF mutation, this rate was found to be only 3.5% among 57 patients with OMM." (PMID 38139110, 2023). "BRAF (V600E) mutation was found to directly regulate HIF-1 expression in cutaneous melanoma." (PMID 37895015, 2023). "Four major genetic subtypes of cutaneous melanoma have been proposed by The Cancer Genome Atlas according to frequently detected hot-spot mutations: mutant BRAF, mutant RAS, mutant NF1, and triple wild-type (TWT), characterized by a lack of BRAF, RAS, or NF1 mutations." (PMID 37239381, 2023).